FCGR2B (Fc gamma receptor IIb)
Diseases named in the same sentence as FCGR2B in open-access papers (continued):
Sharing a sentence is not in itself a finding about the gene and the disease.
lupus (continued). "As such, Syk inhibitor attenuated NETosis (serum dsDNA, MPO, and glomerular NETs) and glomerular apoptosis in Fcgr2b-/- mice at 24 h post renal-I/R affected to decreased glomerular Ig deposition and attenuated lupus activity (anti-dsDNA, proteinuria and Scr) after 120 h post renal-I/R." (PMID 34248948, 2021). "In addition, the inhibitors against Syk and PAD4 attenuated lupus characteristics (serum creatinine, proteinuria, and anti-dsDNA) in Fcgr2b-/- mice at 120 h post-renal I/R injury." (PMID 34248948, 2021). "The lupus-prone mouse model used in the study was C57BL/6 mice congenic for New Zealand black (NZB) autoimmunity 2 (Nba2) locus on chromosome 1, that peaked at the FcgR2b gene encoding FcgammaRIIB." (PMID 33110193, 2020). "Next we studied whether the serum IgG glycosylation differs between lupus-prone Fcgr2b−/− mice and 56R+/−Fcgr2b−/− mice." (PMID 29928274, 2018). "Fcgr2b may play a role in the maintenance of peripheral tolerance and its polymorphism is, like that of BANK-1, significantly associated with systemic lupus erythematosus (SLE)." (PMID 24427159, 2013). "In particular, single nucleotide polymorphisms (SNPs) in FCGR2A (R131H), FCGR2B (I232T) FCGR3A (V158F) and FCGR3B (NA1/NA2), have been reported in association with systemic lupus erythematosus (SLE), rheumatoid arthritis (RA) and/or idiopathic thrombocytopenia purpura (ITP)." (PMID 20957197, 2010). "Additionally, Fcgr2b-/- mice develop age-dependent lupus characteristics, including asymptomatic lupus prone (less than 16 weeks old), asymptomatic lupus with anti-dsDNA (16-24 weeks old) and full-blown lupus (40 weeks old), which have been used as a representative model of lupus." (PMID 34248948, 2021). "We found that IL-1β induction by Fcgr2b−/− BMDMs stimulated with IgG IC was restored to WT levels by the addition of 2DG, suggesting that it may potentially ameliorate macrophage-induced inflammation in lupus." (PMID 32541026, 2020). "Treatment with ISD017 and CYC reduced the mortality of Fcgr2b-deficient lupus mice with a comparable survival rate, suggesting that ISD017 could be a therapeutic drug for SLE." (PMID 38745067, 2024). "Complete Fcgr2b-KO mice on the C57BL/6 background spontaneously develop autoantibody titers and develop a fulminant lupus phenotype, probably due to combined effects on B cells and myeloid cells." (PMID 35819855, 2022). "Interestingly, anti-dsDNA is inducible very shortly after I/R (5 days) in 8-week-old Fcgr2b-/- mice (asymptomatic lupus prone mice), despite the low-level of anti-dsDNA at baseline which is similar to the level in WT mice, indicating the existence of auto-reactive B cells in Fcgr2b-/- mice." (PMID 34248948, 2021). "KEGG analysis revealed the systemic lupus erythematosus pathway involving CD86, TNF, C4, FCGR2B, CD80, C3, CD40, and C1S." (PMID 28976997, 2017). "Surprisingly, in spite of the high frequency of the FCGR2B-232T allele in our population, our study did not highlight any association of this allele either with SLE or lupus nephritis (a severe and frequent form of SLE)." (PMID 40728959, 2025). "Previous studies have utilized a newly developed STING inhibitor molecule (ISD017) in lupus mouse models lacking the Fcgr2b gene." (PMID 38745067, 2024). "The rapid elevation of anti-dsDNA in 8-week-old Fcgr2b-/- lupus prone mice after 120 h post-I/R suggesting the non-specific activation of autoreactive B cells in Fcgr2b-/- mice post-renal I/R that was similar to a previous publication." (PMID 34248948, 2021). "For example, FCGR3A, FCGR2B and HLA-DQA1 may function via the systemic lupus erythematosus pathway, and AMY2B and AMY2A may participate in lung SCC via starch and sucrose metabolism pathway." (PMID 26297502, 2015).
lupus (continued). "Since we previously showed that increases in ANA+ IgG PCs in patients with SLE and lupus-prone mice occur through aberrant IgG PC differentiation rather than as a result of an antigen-specific tolerance defect, we also analyzed tolerance checkpoints for ANA+ B cells and PCs in Fcgr2b-cKO mice." (PMID 35819855, 2022).
autoimmune disease (62 papers, 2006 to 2025). A disorder resulting from loss of function or tissue destruction of an organ or multiple organs, arising from humoral or cellular immune responses of the individual to their own tissue constituents. "FCGR2B is a risk factor to systemic lupus erythematous which is an autoimmune disease, and to other bacterial infections including tuberculosis and have also been identified as a candidate loci for selection in our study." (PMID 38409353, 2024). "Examples of autosomal genes with a female bias in macrophages include Fcgr2b, Samd9l, and Ccr5, which have been implicated in autoimmune diseases." (PMID 38496477, 2024). "Deficiency of Fcgr2b is associated with several autoimmune diseases including SLE, RA, anti-glomerular basement membrane (GBM) disease, and multiple sclerosis (MS)." (PMID 35963953, 2022). "The I232T (isoleucine changed to threonine at position 232) missense mutation on FCGR2B caused by a single-nucleotide polymorphism is associated with susceptibility to autoimmune diseases such as systemic lupus erythematosus." (PMID 36685974, 2022). "Polymorphisms in the FCGR2B promoter or transmembrane domain of FcγRIIB influence receptor expression and signaling potency and are associated with susceptibility to autoimmune diseases including SLE, Goodpasture's disease, ITP, and RA." (PMID 30941127, 2019). "We have compared them to Fcgr2b−/− mice carrying the STINGgt mutation because STING has regulatory roles in development of autoimmune diseases in several models including antigen-induced arthritis, autoimmune encephalomyelitis, and SLE." (PMID 31681326, 2019). "Noteworthy variation in the gene encoding FCGR2B has been associated with susceptibility to autoimmune disease such as RA and SLE." (PMID 26086874, 2015). "Additionally, mice with a specific deletion of Fcgr2b in DCs displayed enhanced immune responses and increased susceptibility to autoimmune diseases." (PMID 37176021, 2023). "Therefore, the dysfunction of FCGR2B affects the susceptibility to several autoimmune diseases." (PMID 32500465, 2020). "Moreover, HP infection down-regulates the expression of Fc gamma receptor IIb (FcγRIIb), the only inhibitory FcγR on circulating monocyte of patients with autoimmune diseases." (PMID 30034379, 2018). "FcγRIIb expression can impair immunotherapy efficacy in vivo by suppressing activating FcγR signalling whilst the FCGR2B-232I/T SNP in the transmembrane domain of FcγRIIb impairs its inhibitory function and has been implicated in predisposition to autoimmune disease." (PMID 26545243, 2015). "In the studies of genetic predisposition to develop autoimmune disorders, CNV was proven only for FCGR2C, FCGR3A and FCGR3B, but not for FCGR2A and FCGR2B genes." (PMID 28472129, 2017).
Autoimmunity (45 papers, 2008 to 2025). The occurrence of an immune reaction against the organism's own cells or tissues. "To better understand how MAVS deficiency prevents autoimmunity in Fcgr2b-deficient mice, we focused on B cell activation because previous data implicated a B cell–intrinsic effect." (PMID 37610299, 2023). "We previously generated a knock-in mouse model bearing naturally occurring polymorphisms of the Fcgr2b promoter common in wild mice and associated with spontaneous autoimmunity in inbred strains." (PMID 31036800, 2019). "Considering this possibility, one could predict that FCGR2B-Stop alleles were also formed in this way, but the rarity of FCGR2B-Stop alleles suggests great evolutionary pressure on this variant, which may be associated with severe autoimmunity." (PMID 31632391, 2019). "Mouse strains with targeted Fcgr2b deletions have been extensively studied on different models resulting in diverse reports regarding its role in autoimmunity." (PMID 35963953, 2022). "The second most relevant cross-talk gene was FCGR2B, which is an inhibitory receptor with a central role in the regulation of autoantibody generation and thus autoimmunity." (PMID 34858391, 2021). "It has also been speculated that unexplained cases of early onset severe autoimmunity may result from homozygous deletion of CNR4 because the FCGR2B‐stop variant would not be detected by NGS techniques as all FCGR2B‐stop reads would be mapped to the FCGR2C gene instead." (PMID 39345014, 2024). "We next wondered if this bystander autoimmunity could be observed in a more physiological context, and thus performed similar experiments with the SWHEL-FcγRIIbwild/H1 KI mice containing naturally occurring promoter Fcgr2b variations." (PMID 31036800, 2019).
Arthritis (29 papers, 2006 to 2024). Inflammation of a joint. "Previous studies have shown that FCGR2B deficiency activates autoreactive T cells to develop arthritis." (PMID 39734218, 2024). "First, we established CAIA in BQ.Fcgr2b- mice, which are highly susceptible to arthritis, by the transfer of a cartilage antibody cocktail containing 4 monoclonal antibodies (Cab4)." (PMID 37741824, 2023). "We have previously shown that the pathogenic effect of anti-COL2 antibodies is downregulated by FCGR2B, and we confirmed this also in BQ.Col2266E mice, which is much more susceptible to collagen antibody-induced arthritis (CAIA) if deficient in Fcgr2b." (PMID 35963953, 2022). "As expected, insertion of Ncf1m1j/m1j especially Fcgr2b−/− enhanced the susceptibility to arthritis." (PMID 35963953, 2022). "Evidence has suggested that Fcgr2b is closely associated with arthritis-related joint pain, anterior cingulate cortex and prefrontal cortex alteration after nerve injury, and stroke in aged rats." (PMID 36340779, 2022). "In conclusion, the new human-mimicking mouse model has strong T cell tolerance to COL2, which can be broken by deficiency of Fcgr2b or Ncf1, allowing activation of autoreactive T cells and development of arthritis." (PMID 35963953, 2022). "Moreover, FCGR2B deficiency counteracts Hc encoding complement C5 action to accelerate the rapid progression of arthritis." (PMID 39734218, 2024). "Importantly, we found that BQ.Col2266E.Fcgr2b−/− mice developed severe arthritis with high incidence while Ncf1m1j/m1j mutation allowed the development of arthritis in mice with the D266E mutation but with much milder disease." (PMID 35963953, 2022). "Thus, both Ncf1 and Fcgr2b deficiency contributed to the arthritis susceptibility." (PMID 35963953, 2022). "Fcgr2b−/−.Ncf1m1j/m1j developed the most severe arthritis with early onset and 100% incidence, compared with other strains." (PMID 35963953, 2022). "To study whether they could break T cell tolerance and allow the development of CIA driven by autoreactive T cells, we intercrossed Fcgr2b and Ncf1 deficient mice with the BQ.Col2266E strain and found that both genes could additively break the T cell tolerance and allow the development of arthritis." (PMID 35963953, 2022). "As both Fcgr2b and Ncf1 protected against the breach of T cell tolerance and development of arthritis, we next addressed the possibility that they operate in the same pathway, i.e., that they epistatically interact." (PMID 35963953, 2022). "The interaction between Fcgr2b and Ncf1 was additive, indicating that the pathways whereby they influence arthritis are mainly independent on each other." (PMID 35963953, 2022). "This implies the existence of a protective effect of FCGR2B against arthritis." (PMID 39734218, 2024). "Therefore, we made new cross-breeding on the BQ.Col2266E or B10Q background inducing deficiency of both Fcgr2b and Ncf1 and immunized them with COL2 together with control groups, then recorded the development of arthritis." (PMID 35963953, 2022). "CD55 deficiency did not enhance K/BxN serum-induced arthritis, but further exaggerated disease activity in Fcgr2b−/− mice." (PMID 25596646, 2015).
lupus nephritis (24 papers, 2008 to 2025). Glomerulonephritis in the context of systemic lupus erythematosus. "The administration of a STING inhibitor (ISD017) into the young 129.B6.Fcgr2b-deficient mice prevents lupus nephritis development." (PMID 38745067, 2024). "ISD017 worked comparably to cyclophosphamide for treating lupus nephritis in 129.B6.Fcgr2b-deficient mice." (PMID 38745067, 2024). "We opted to focus on anti-dsDNA antibodies due to their noted association with the lupus nephritis phenotype and anti-dsDNA change in a previous paper on the double deficiency of Fcgr2b and Sting mice." (PMID 38745067, 2024). "We conducted a detailed analysis of the association between FCGR2A, FCGR2B, FCGR3A and FCGR3B polymorphisms and lupus nephritis." (PMID 40728959, 2025). "A mouse model of lupus nephritis induced by Fcgr2b-/- was used to establish an IRI-induced AKI model." (PMID 41169399, 2025). "Control Fcgr2b-/- mice that received PBS apparently showed lupus nephritis as indicated by renal tubulointerstitial injury scores based on tubular vacuolization and increased infiltration of interstitial cells (second row)." (PMID 37176021, 2023). "Fcgr2b-/- mice spontaneously developed full-blown lupus nephritis (impaired renal function, proteinuria, and increased anti-dsDNA) at 40 weeks old without polyarthritis and serositis (data not shown)." (PMID 34248948, 2021). "Reduced IgG sialylation was especially evident in Fcgr2b−/− mice that developed signs of lupus nephritis (proteinuria and kidney inflammation)." (PMID 29928274, 2018). "Although the renal I/R induced the renal excretory dysfunction (serum creatinine) at 24 h post-renal I/R of Fcgr2b-/- mice was similar to those of wild type (WT) mice, there was higher NETs and apoptosis in glomeruli which led to lupus nephritis possibly through Syk signaling after 120 h post-I/R." (PMID 34248948, 2021).
malaria (21 papers, 2014 to 2025). Malaria is a serious and sometimes fatal disease caused by a parasite that commonly infects a certain type of mosquito which feeds on humans. "For example, FCGR2A-131H and FCGR2B-232T alleles are associated with a protective effect against malaria and against its most deadly forms." (PMID 40728959, 2025). "FCGR2B protein demonstrated moderate discriminatory ability (AUC = 0.717), suggesting a notable but less pronounced association with malaria status compared to IL-20." (PMID 40697816, 2025). "The FCGR2B-p.Thr232Ile change (rs1050501) alters CD32B affinity for lipid rafts, thereby limiting its inhibitory function, and it seems to improve survival in malaria, while increasing susceptibility to SLE and childhood idiopathic thrombocytopenia." (PMID 34108956, 2021). "Although NRTN expression levels may still have some association with malaria status, the association is less pronounced compared to IL-20, FCGR2B, and HO-1." (PMID 40697816, 2025). "In addition to these, we genotyped the coding variants FCGR2A/rs1801274 and FCGR2B/rs1050501 in 234 individuals from a malaria-endemic area in Burkina Faso." (PMID 37958695, 2023). "SNP rs1050501 in the FCGR2B gene may be under the influence of evolutionary pressure caused by malaria." (PMID 33281811, 2020). "Moreover, the complement factor 1 (CR1) gene, suggested to be involved in malaria susceptibility, and the FCGR2B gene, demonstrated to harbor malaria protective alleles, were also identified by our analysis, thus strengthening the mark of malaria in the Italian genome." (PMID 26553317, 2015). "Using proximity extension assay (PEA), we identified elevated IgG Fc receptor IIb (FCGR2B) and heme oxygenase-1 (HO-1) in malaria-positive pregnancies, while neurturin (NRTN) and IL-20 were downregulated." (PMID 40697816, 2025). "FCGR2B is known to be a resistance factor to malaria and FCGR3A is involved in autosomal recessive immunodeficiency." (PMID 38409353, 2024). "In malaria-exposed children we found that T-bethi B cells express markers that are known to be associated with atypical MBCs (FCRL5, FCGR2B, CD11c, CXCR3 and CD95)." (PMID 28953967, 2017). "We observed that FCGR2B, HO-1, NRTN and IL-20 were differentially expressed in plasma from malaria-infected pregnant women vs. from non-malaria-infected controls." (PMID 40697816, 2025). "This study focused on three SNPs in the FcγRs gene cluster that are yet to be studied in relation to malaria: two intronic SNPs (FCGR2C-rs3933769 and FCGR3A-rs396991) and a functional SNP in the FCGR2B-rs1050519." (PMID 26785902, 2016).
Allergy (18 papers, 2010 to 2025). An allergy is an immune response or reaction to substances that are usually not harmful. "Fc gamma receptor IIb (FcγRIIb), an inhibitory IgG receptor, has recently emerged as a negative regulator of allergic diseases like anaphylaxis and allergic rhinitis." (PMID 20179765, 2010). "In addition, a functional single nucleotide polymorphism (SNP) in the inhibitory FCGR2B was found to be associated with atopy and increased IgE production, suggesting that FCGR2B SNP may have a role in allergy and IgG4-RD via its effects on IgE production." (PMID 34305927, 2021). "FCGR2B and FCER1G are immunoglobulin fragments that regulate the immune response, and increase the likelihood of obese patients developing allergic diseases." (PMID 34093637, 2021).
melanoma (18 papers, 2010 to 2025). A malignant, usually aggressive tumor composed of atypical, neoplastic melanocytes. "Only FCGR2B has been identified to be selectively expressed by metastasis melanoma that impairs the tumor susceptibility to FcγR-dependent innate effector responses, which might explain in part the low response of melanoma patients treated with anti-idiotype." (PMID 35372055, 2022). "In the same study, it was also shown that CD8+ T-cells in melanoma patients express FCGR2B, proposing its role in down-regulating tumor-directed immune responses in humans." (PMID 36291815, 2022). "First, we investigated whether SIGLEC10 and FCGR2B are highly expressed within the B cell population in human melanomas." (PMID 40894037, 2025). "Interestingly, in a melanoma mouse model, FCGR2B has been demonstrated to be upregulated in tumor-infiltrating CD8+ T-cells hampering their antitumor efficacy." (PMID 36291815, 2022). "In our previous studies, Fcgr2b–/– OVA-specific CD8+ T cells outcompeted WT OVA-specific CD8+ T cells in a WT mouse in the context of skin graft and melanoma." (PMID 40125553, 2025). "In the melanoma dataset, we found that the FCGR2B pathway is strongly upregulated in non-responders." (PMID 33065980, 2020). "Studies using a mouse B16 melanoma model have further demonstrated a higher efficacy of the protective IgG2a antibody TA99 in Fcgr2b–/– mice compared with WT mice, as demonstrated by an approximately 30-fold greater reduction in the volume of lung metastases in Fcgr2b–/– mice compared with WT mice." (PMID 33616086, 2021).